RNF5 (ring finger protein 5)
Description:
Membrane-bound E3 ubiquitin-protein ligase that mediates ubiquitination of target proteins. May function together with E2 ubiquitin-conjugating enzymes UBE2D1/UBCH5A and UBE2D2/UBC4. Mediates ubiquitination of PXN/paxillin,thereby regulating cell motility and localization of PXN/paxillin. Catalyzes ubiquitination of Salmonella type III secreted protein sopA. Mediates the 'Lys-63'-linked polyubiquitination of JKAMP thereby regulating JKAMP function by decreasing its association with components of the proteasome and ERAD; the ubiquitination appears to involve E2 ubiquitin-conjugating enzyme UBE2N. Mediates the 'Lys-48'-linked polyubiquitination of STING1 at 'Lys-150' leading to its proteasomal degradation; the ubiquitination occurs in mitochondria after viral transfection and regulates antiviral responses. Catalyzes ubiquitination and subsequent degradation of ATG4B, thereby inhibiting autophagy.
Synonyms: G16; NG2; RMA1; RING5
Tractability: Antibody: UniProt places it where antibodies can reach, with high confidence; UniProt predicts a signal peptide or a membrane-spanning region; its Gene Ontology location is reachable by antibodies, with medium confidence. PROTAC: ubiquitination databases record sites on it.
Target class: Enzyme; Transferase
Gene: Protein-coding gene on chromosome 6 (32,178,405 to 32,180,793, forward strand). Ensembl gene ENSG00000204308.
Subcellular location: Cell membrane; Mitochondrion membrane; Endoplasmic reticulum membrane
Subcellular location (Human Protein Atlas): Endoplasmic reticulum
Pathways (Reactome):
Disease: Defective CFTR causes cystic fibrosis
Immune System: AMPK-induced ERAD and lysosome mediated degradation of PD-L1(CD274)
Metabolism of proteins: ER Quality Control Compartment (ERQC)
Transport of small molecules: ABC-family protein mediated transport
Gene Ontology:
Molecular function: identical protein binding; protein binding; protein-containing complex binding; ubiquitin protein ligase activity; ubiquitin-protein transferase activity; ubiquitin-like protein conjugating enzyme binding; zinc ion binding
Biological process: ERAD pathway; protein catabolic process; protein K48-linked ubiquitination; protein K63-linked ubiquitination; ubiquitin-dependent protein catabolic process; endoplasmic reticulum mannose trimming; transmembrane transport; protein ubiquitination
Cellular component: endoplasmic reticulum; endoplasmic reticulum membrane; mitochondrial membrane; plasma membrane; endoplasmic reticulum quality control compartment; membrane
Genetic constraint (gnomAD): Loss-of-function variants: 16 observed, 23.98 expected, observed/expected ratio (o/e) 0.67, 90% interval 0.45 to 1.01. The upper end of that interval is the gene's LOEUF score, 1.01, which puts it in group 4 of 6, group 1 being the genes least tolerant of losing a copy. Missense variants: 185 observed, 235.63 expected, observed/expected ratio (o/e) 0.79, 90% interval 0.7 to 0.89. Synonymous variants: 64 observed, 84.27 expected, observed/expected ratio (o/e) 0.76, 90% interval 0.62 to 0.94.
Homologues: Orthologues: chimpanzee RNF5 (100% identical), macaque RNF5 (99% identical), pig RNF5 (99% identical), dog RNF5 (98% identical), guinea pig RNF5 (98% identical), mouse Rnf5 (98% identical), rat Rnf5 (98% identical), rabbit RNF5 (97% identical), tropical clawed frog rnf5 (65% identical), zebrafish RNF5 (62% identical), Drosophila melanogaster sordd1 (49% identical), Drosophila melanogaster sordd2 (48% identical), and 2 more. Paralogues in human: RNF185 (59% identical).
Diseases named in the same sentence as RNF5 in open-access papers:
RNF5 is named in the same sentence as 55 diseases in open-access papers, as found by Europe PMC text mining. Sharing a sentence is not in itself a finding about the gene and the disease. The quoted sentences say what the papers report.
viral infection (19 papers, 2014 to 2025). "Viral infection enhanced RNF5 interaction with STING, leading to STING K48-linked polyUb and proteasomal degradation to evade the innate immune response." (PMID 37938264, 2023). "Due to the complex formation of structural proteins VP1, VP2, and VP3 under viral infection, we conducted immunoblot experiments to investigate the effects of RNF5 on the expression of VP2 and VP3 proteins." (PMID 39823440, 2025). "The results showed that RNF5-KO cells inhibited their ubiquitin levels during the process of viral infection compared to WT cells, indicating that RNF5 also mediated ubiquitination of VP2 and VP3." (PMID 39823440, 2025). "Viral infection stimulates the expression of the E3 protein-ubiquitin ligase ring finger protein 5 (RNF5)." (PMID 38675916, 2024). "The most significant signal was for RNF5, which is involved in the degradation of misfolded proteins and regulation of viral infection." (PMID 38466119, 2024). "The Ring Finger Protein 5 (RNF5) is a membrane-bound ubiquitin ligase that is known to inhibit IFN type I in the context of virus infections." (PMID 38140653, 2023). "It is possible that after activation of VISA-mediated signaling at the early phase of viral infection, the release of the antagonizing effects of iRhom2 on RNF5 and/or MARCH enables them to degrade VISA." (PMID 29155878, 2017). "We found that different from the association between RNF5 and VISA, which occurs mostly in un-infected and early-infected cells, MARCH5 was associated with VISA at late phase of viral infection." (PMID 29155878, 2017). "Our findings suggest that RNF5-mediated VP1 protein degradation could serve as a potential therapeutic approach for treating virus infections." (PMID 39823440, 2025). "Our study reveals a novel mechanism of IFITM against virus invasion and suggests RNF5 as well as ABHD16A may act as promising therapeutic targets for the intervention of virus infection." (PMID 39601593, 2025). "In conclusion, our study demonstrated that swine RNF5 interacted and ubiquitinated sABHD16A for degradation, which then attenuated the depalmitoylation effects on sIFITM1 and consequently promoted the activity of sIFITM1 against virus infection." (PMID 39601593, 2025). "This comprehensive understanding could offer valuable insights into exploring potential therapeutic applications focused on targeting RNF5 during viral infections." (PMID 38250078, 2023). "Notably, RNF5 acts as an emerging negative regulator of antiviral innate immunity, which is the host’s first line of defense against virus infections." (PMID 38250078, 2023). "Finally, we will discuss potential therapeutic approaches targeting RNF5 to modulate immune responses and combat viral infections." (PMID 38250078, 2023). "RNF5 associates with STING and ubiquitinates STING at Lys150 for K48-linked ubiquitination and proteasomal degradation after viral infection, denoting the important role of RNF5 in dampening virus-triggered IFN-I induction by targeting both MAVS and STING degradation." (PMID 36042206, 2022). "These indicate that JMJD6 catches RNF5 to degrades IRF3 in the nucleus upon viral infection." (PMID 33684176, 2021). "Further experiments indicated that RNF26 protected MITA from RNF5-mediated K48-linked polyubiquitination and degradation that was required for quick and efficient type I IFN and proinflammatory cytokine induction after viral infection." (PMID 25254379, 2014). "Therefore, RNF5 plays multiple roles in virus-host interaction, and it appears important to ascertain whether and how the interaction between ABHD16A and RNF5 influences IFITMs-mediated virus infection." (PMID 39601593, 2025). "In conclusion, severe viral infection could induce ER stress to promote STING degradation by upregulating RNF5 and to reduce STING production by inducing apoptosis of immune cells, resulting in STING deficiency and immune response disorder, which ultimately may trigger AE-IPF." (PMID 29312299, 2017).
viral infection (continued). "The results showed that RNF5-KO cells increased the VP2 and VP3 expression during the process of viral infection compared to WT cells, indicating that RNF5 also mediated the degradation of VP2 and VP3." (PMID 39823440, 2025). "Accumulating evidence has indicated that RNF5 targets several innate immune regulators, including MAVS, STING, and IRF3 for degradation, thus facilitating virus infection (19, –, 21)." (PMID 39601593, 2025). "For example, RNF5, RNF122, and RNF215 have been shown to negatively regulate NF-κB-, RIG-I-, or STING-mediated IFN responses during viral infection." (PMID 40261845, 2025). "We focused on SHARPIN and RNF5 as candidate hits for ORF3, as they are involved in the RLR-MAVS pathway and interferon (IFN) induction during viral infections." (PMID 38140653, 2023). "Conversely, the regulation of RNF5 and its interaction with STING and MAVS presents potential therapeutic avenues for modulating immune responses and combating viral infections." (PMID 38250078, 2023). "JMJD6 plays a crucial role in recruiting RNF5 and IRF3, facilitating their translocation from the cytoplasm to the nucleus upon viral infection." (PMID 38250078, 2023). "A second candidate interactor of ORF3 that we selected was RNF5, especially because this protein has also been described to influence IFN induction in context of viral infections." (PMID 38140653, 2023). "Previous studies have demonstrated that RNF5 inhibits the activation of IRF3 and NF-κB signaling pathways by mediating the ubiquitination and degradation of STING triggered by viral infection to avoid excessive antiviral responses." (PMID 36270989, 2022). "The E3 ligase RNF5 has been reported to target STING-K150 for ubiquitination and degradation upon viral infection, a process that can be antagonized by RNF26-mediated STING-K150 ubiquitination, presumably through a non-K48 linkage." (PMID 35795661, 2022). "Our findings provide new insights into the mechanisms of IFITMs fighting against virus; demonstrate the importance of RNF5, ABHD16A, and IFITM interplay in balancing antiviral immune responses; and provide broad-spectrum therapeutic strategies for animal viral diseases." (PMID 39601593, 2025). "Moreover, RNF5 and IRF3 showed significant translocation from the cytoplasm into the nucleus upon viral infection, which indicates that JMJD6 recruits RNF5 and IRF3 together in the nucleus upon viral infection." (PMID 33684176, 2021). "Mechanistically, iRhom2 was reported to induce auto-ubiquitination of the E3 ligase RNF5 either in the absence of viral infection or during early viral infections (4h)." (PMID 32911849, 2020). "Severe viral infection may trigger UPR and ER stress, inducing RNF5 over-expression so to promote STING degradation via ubiquitination." (PMID 29312299, 2017). "Interestingly, we found that among these E3 ligases, iRhom2 specifically reduced the protein levels of RNF5 and MARCH5 in different phases of viral infection." (PMID 29155878, 2017).
breast carcinoma (17 papers, 2014 to 2026). "As an ER-associated E3 ubiquitin ligase, RNF5 demonstrates widespread expression in various cells and tissues, with the highest expression in breast cancer and melanoma." (PMID 38250078, 2023). "In fact, the increase in RNF5 expression is associated with poor prognosis and survival of breast cancers and hepatocellular carcinoma, and RNF5 degrades PTEN to promote pancreatic tumor growth." (PMID 37816703, 2023). "Accordingly, high expression of RNF5 was associated with positive prognosis in breast cancer patients." (PMID 35406574, 2022). "Altogether, these results suggest that high EphA2 expression is associated with longer survival of HER2-negative breast cancers with low RNF5 expression, in which leads to that EphA2 acts as a tumor suppressor and improved prognosis under RNF5 inhibition in ER-positive HER2-negative breast cancers." (PMID 37816703, 2023). "RNF5 is an E3 ubiquitin ligase which has been associated with focal adhesion as well as endoplasmic reticulum stress response, and is proposed to be a regulator of breast cancer progression through its effects on actin cytoskeleta." (PMID 24647608, 2014). "Our studies not only reveal the importance of RNF5 in regulation of EphA2 tumor-suppressive function in breast cancers, but also provide a promising clue to develop novel chemotherapy for ER-positive HER2-negative breast cancers." (PMID 37816703, 2023). "RNF5 expression is inversely correlated with EphA2 expression in breast cancers, and a high EphA2 level accompanied by a low RNF5 level is related to better survival in patients with ER-positive, HER2-negative breast cancers." (PMID 37816703, 2023). "We investigated the effect of the RNF5-EphA2 level in breast cancers, and then, the survival of breast cancer patients was analyzed with RNF5 and EphA2 levels." (PMID 37816703, 2023). "In the present study, we confirmed the tumor-suppressive effect of RNF5 inhibition in estrogen receptor-positive HER2-negative breast cancers." (PMID 37816703, 2023). "Studies have shown that the lower level of RNF5 expression in breast cancers is related to the longer survival of patients." (PMID 37816703, 2023). "As a consequence, increased EphA2 level and altered EphA2 phosphorylation induced by selective RNF5 inhibition decreases the tumorigenesis of HER2-negative breast cancers." (PMID 37816703, 2023). "The analysis of RNA-seq levels from TCGA database showed that RNF5 was negatively correlated with EphA2 (coefficients < 0, p < 0.01) in breast cancers." (PMID 37816703, 2023). "To further investigate the effect of RNF5-regulated EphA2 level, we measured EphA2 phosphorylation and several downstream pathways in RNF5 WT vs. KD breast cancer cells." (PMID 37816703, 2023). "RNF5 depletion resulted in increased adhesion in four lines of HER2-negative breast cancer cells, while EphA2 depletion decreased adhesion and abolished the increase in adhesion in cells with RNF5 depletion." (PMID 37816703, 2023). "Altogether, these results indicate that RNF5 promotes the tumorigenesis of HER2-negative breast cancer cells by decreasing the EphA2 level." (PMID 37816703, 2023). "In contrast to RNF5 pro-tumor activity, in breast cancer, RNF5 promoted ubiquitination and degradation of glutamine transporters SLC1A5 and SLC38A2, which were aberrantly folded following chemotherapy-induced ER stress." (PMID 35406574, 2022). "In breast cancer, RNF5 is involved in the degradation of glutamine transporters SLC1A5 and SLC38A2, which are aberrantly folded following chemotherapy-induced ER stress." (PMID 35406574, 2022).
breast carcinoma (continued). "In agreement with our results, breast cancer patients with high expression of RNF5 and low expression of the glutamine transporter SLC1A5 were associated with better prognosis than tumors expressing high SLC1A5 and low RNF5." (PMID 35406574, 2022). "Increased expression of RNF5 was observed in different malignancies including breast cancer, melanoma, hepatocellular carcinoma and acute myeloid leukemia (AML) where it correlated with poor prognosis and tumor progression." (PMID 35406574, 2022). "RNF5 expression is relatively increased in several cancers, including breast cancer, hepatocellular carcinoma, and AML7." (PMID 34518534, 2021). "Breast cancer, in particular, has been previously shown to over-express RNF5, whereas other cancers have yet to be explored." (PMID 30456390, 2018). "This degradation is specifically mediated by the ubiquitin ligase RNF5 and ultimately leads to mTOR inactivation, autophagy and apoptosis of breast cancer cells." (PMID 26425657, 2015). "To further investigate the effects of RNF5-regulated EphA2 in the tumorigenesis of breast cancer cells, we investigated whether RNF5 affects the adhesion of HER2-negative breast cancer cells." (PMID 37816703, 2023). "Further analysis of dysfunctions in breast cancers and mining of emerging tumor databases may define the mechanisms, applications and limitations of RNF5-targeted therapy." (PMID 37816703, 2023). "Moreover, RNF5 depletion in breast cancer cells promotes tumorigenesis and eliminates paclitaxel resistance." (PMID 37190313, 2023). "Furthermore, the migration of breast cancer cells was measured in a transwell assay under conditions of RNF5 knockdown and/or EphA2 knockdown." (PMID 37816703, 2023). "Ring finger protein 5 (RNF5), also known as RMA1, is an 18 kDa E3 ligase localized on the cytoplasmic surface of the endoplasmic reticulum and is ubiquitously expressed in diverse cells and tissues, with the highest expression in breast cancer and melanoma." (PMID 36656913, 2023). "An increase in the EphA2 level was induced by RNF5 shRNA in the three breast cancer cell lines, and the phosphorylation of EphA2 at S897 was decreased while that at Y772 was increased in RNF5 KD cells of all cell lines compared with the corresponding RNF5 WT cells (top)." (PMID 37816703, 2023). "PHGDH is also a ubiquitination substrate of RNF5 in the study of breast cancer cells." (PMID 34350460, 2021). "Analysis of patients with breast cancer showed that the expression status of the estrogen receptor might determine the role of RNF5 in breast cancers and that low RNF5 expression was correlated with better overall survival in patients with estrogen receptor-positive breast cancers." (PMID 37816703, 2023). "Overall, RNF5 modulates EphA2 level and tumor-suppressor function to facilitate tumor formation of HER2-negative breast cancers." (PMID 39596256, 2024). "Mass spectrometry analysis demonstrated that the E3 ligase RNF5 directly interacted with EphA2 and induced EphA2 ubiquitination and degradation in HER2-negative breast cancer cells, thereby suppressing EphA2 tumor-suppressive functions in this neoplasia." (PMID 39596256, 2024). "The degradation of PHGDH by ring finger protein 5 inhibited breast cancer cell growth, and the acetylation of PHGDH at K58 disrupted the interaction between ring finger protein 5 and PHGDH and promoted breast cancer cell proliferation." (PMID 38945960, 2024).